SDC1 (syndecan 1)
Diseases named in the same sentence as SDC1 in open-access papers (continued):
Sharing a sentence is not in itself a finding about the gene and the disease.
tumor (continued). "In this direction, mice with a null mutation in SDC1 are protected from carcinogen-induced tumor development." (PMID 27434331, 2016). "Syndecan-1 has been implicated in tumor cell migration and undergoes limited proteolysis at the surface and within the membrane of tumor cells." (PMID 26378057, 2015). "High serum SDC1 levels were significantly associated with greater risk of tumor recurrence and decreased overall survival in patients with early HCC and with advanced HCC, respectively." (PMID 26293675, 2015). "The analysis of tumor tissues taken from mice treated with OC-46F2 as monotherapy or combination therapy confirms that the anti Syndecan-1 antibody inhibits vascular maturation and induces loss of VM structures." (PMID 26460958, 2015). "Further evidence indicated strong staining of SDC1 in DCIS tumor samples, which was associated with E-cadherin and c-Met expression." (PMID 26293675, 2015). "Decreased syndecan-1 expression in epithelial cells is associated with tumor aggressiveness and poor survival in squamous cell head and neck carcinoma." (PMID 26420915, 2015). "On the other hand, there are studies showing that syndecan-1 immunopositivity is associated with tumor size." (PMID 26420915, 2015). "Additional studies showed that loss of epithelial SDC1 expression was associated with high stromal SDC1 expression, higher tumor grade, poor overall survival, and nodal metastases." (PMID 26293675, 2015). "This characterizing trait of the SDC1 tumour-associated expression was corroborated here, along with its widespread distribution in neoplastic HNSCC lesions." (PMID 25935541, 2015). "Syndecan-1 association with integrins seems to generally induce tumor cell spreading and invasion, especially via interaction of its extracellular domain with αVβ3 and αVβ5 integrins." (PMID 26558271, 2015). "In tumor initiating cells and mouse model in contrary, it was found that syndecan-1 immunopositivity is associated with recurrence and it has a role in maintaining tumor stem cells." (PMID 26420915, 2015). "The loss of SDC-1 at the cell surface by extracellular cleavage can decrease the strength of tumor cell adhesion within the tissue architecture, resulting in an increase in cellular motility." (PMID 24524203, 2014). "Syndecan-1 has been associated with tumor suppressor function, and its expression is downregulated in a variety of cancer tissues." (PMID 23705906, 2013). "Our results also revealed that a large number of CD68+ tumor-associated macrophages were present in the tumor microenvironment of poor outcome tissue samples in which the CD30+ cells overexpressed both SDC1 and FGF2." (PMID 23988031, 2013). "In our case tumor cell showed loss of E-cadherin and beta-catenin while syndecan-1 expression was reduced and confined on small group of detached malignant cell." (PMID 21223553, 2011). "In an attempt to dissect the contribution of the different functional protein domains of this PG, the two mesenchymal tumor cell lines were transfected with three truncated variants of syndecan-1." (PMID 21731601, 2011). "Combined analysis of syndecan-1 in relation to a potential prognostic biomarker, fascin, identified that loss of tumor syndecan-1 correlated significantly with strong stromal fascin staining." (PMID 18590537, 2008). "Although these studies implicated tumor suppressor roles of syndecan-1, the relationship of syndecan-1 expression to tumor progression or clinical outcomes in human carcinomas has proved to be more complex." (PMID 18590537, 2008). "Combined analysis of syndecan-1 in relation to a recently identified potential prognostic biomarker, fascin, identified a subset of tumors in which loss of tumor cell syndecan-1 correlates significantly with up-regulation stromal of fascin." (PMID 18590537, 2008). "A high syndecan-1 expression in epithelial tumour cells was strongly associated with low histological grade (P<0.011)." (PMID 18542065, 2008).
tumor (continued). "Syndecan-1 null mice are resistant to Wnt1-activated mammary tumors and carcinogen-induced tumor development and have increased susceptibility to allergen-induced airway inflammation." (PMID 18590537, 2008). "Epithelial to mesenchymal transition (EMT) is a major process in tumor progression and loss of expression of syndecan-1 is well established to regulate aspects of EMT." (PMID 18590537, 2008). "The progression of epithelial tumours is characterised by (i) a loss of syndecan-1 expression in tumour cells (EMT) and (ii) a shift of syndecan-1 expression from tumour cells to stroma." (PMID 18542065, 2008). "Intermediate or strong staining for syndecan-1 was associated with a smaller primary tumour size (P = 0.0005) and higher histological grade of differentiation (P = 0.006) than negative or weakly positive staining." (PMID 8054282, 1994). "Background/Objectives: CD138 (syndecan-1) is a cell-surface heparan sulfate proteoglycan involved in cell-matrix interactions and growth factor signaling, and it has been implicated in tumor progression." (PMID 42192900, 2026). "Interestingly, fibroblasts from KPTN tumors were enriched with populations (clusters 6–8) that highly expressed Acta2, Spp1, and Sdc1, which were associated with a tumor-promoting fibroblast phenotype." (PMID 41480763, 2026). "Several studies have indicated that soluble SDC1 is important for tumor cell progression, which contradicts our findings for two reasons: first, in vitro studies lack the tumor microenvironment, and second, SDC1 expressed in stromal cells is associated with immune cells." (PMID 41364407, 2025). "However, increased syndecan 1 expression in breast, pancreatic, ovarian, thyroid, and endometrial tumors is associated positively with tumor development." (PMID 39334952, 2024). "Furthermore, loss of syndecan 1 expression in the majority of epithelial tumors like cervical, lung, head and neck, squamous cell, and esophageal cancers is associated with tumor development and reduced patient survival." (PMID 39334952, 2024). "This indicates that the SDC1/CASP11 expression patterns could determine the susceptibility of cancer cells to SCGB3A2-induced anti-tumor activity." (PMID 33452234, 2021). "Moreover, the appearance of syndecan-1 in the tumor stroma, either associated with its cellular component or the collagenous matrix, is nearly always a sign of poor prognosis." (PMID 33921767, 2021). "Furthermore, it has been demonstrated that syndecan-1 is necessary for the Wnt1 to promote tumor development, indicating its association with the β-catenin/TCF signaling." (PMID 33920054, 2021). "Thus, further studies will be necessary to fully understand the association between HA and SDC-1, taking into account the tumor microenvironment." (PMID 34070901, 2021). "Loss of SDC1 is associated with tumor progression and poor prognosis in a variety of cancers." (PMID 34445387, 2021). "The importance of the HS chains of Sdc-1 in the prevention of tumour spread is exemplified by the heparanase-mediated loss of HS in Sdc-1, which enhances histone acetyltransferase activity and results in gene expression to drive an aggressive tumour cell phenotype." (PMID 33922532, 2021). "Indeed, the downregulation of syndecan-1 expression in PC was associated with the aggressive behavior of these cells and clinical tumor progression." (PMID 32847060, 2020). "Furthermore, increased SDC1 expression of stromal cells was reported as a risk factor for poor clinical outcomes in different tumor types." (PMID 33114033, 2020). "SDC1 was showed to associate with the formation of blood vessels and tumor growth." (PMID 32756007, 2020). "Thus, a higher expression of the Sdc1 in the tumor epithelium of the metastatic IDC is associated with younger patients and a lower expression of both hormone receptors in the primary tumors, which is very significant and can be a basis for further studies." (PMID 30151336, 2018).
tumor (continued). "However, SDC1 can also be found on carcinoma-associated fibroblasts (CAFs) and promote tumor progression." (PMID 30325954, 2018). "On the other hand, syndecan-1 has been associated with a tumor suppressor function." (PMID 30027065, 2018). "Interestingly, in a study of 230 surgical specimens of primary colorectal carcinoma, epithelial positive Syndecan-1 immunostaining was significantly associated with tumor size and EGFR expression." (PMID 28270211, 2017). "The shift of SDC-1 expression from tumour to stromal cells may be associated with a decreased expression within epithelial tumour cells and it can have important consequences." (PMID 25598217, 2015). "Also high level of soluble syndecan-1 generally associates with poor prognosis and it correlates to tumor burden, cancer invasiveness, and risk for metastasis." (PMID 26420915, 2015). "One caveat to keep in mind is that although all pleural metastases represent advanced stages, it could still be that the increase in soluble syndecan-1 merely reflects tumour burden and thereby can be linked to shorter survival." (PMID 25147801, 2014). "Syndecan-1 may exert stimulatory or inhibitory effects, depending on the concentration of various mitogens, enzymes, and signaling molecules, the ratio between the shed and membrane-associated syndecan-1 and histological grade of the tumour." (PMID 24392351, 2013). "Sdc1 has been associated with tumor progression in a number of different tumor cell types." (PMID 22936997, 2012). "Loss of syndecan-1 from tumor cells was most pronounced in the most poorly differentiated tumors." (PMID 18590537, 2008). "However, loss of syndecan-1 immunoreactivity of the tumor did correlate significantly with strong stromal fascin staining." (PMID 18590537, 2008). "Moreover, SDC1 is engaged in malignant biological behaviors, including oncogenesis, invasion, metastasis, and angiogenesis a broad range of tumors, therefore being closely associated with tumor prognosis and therapy response." (PMID 35793235, 2022). "The control of the cell adhesion is partly mediated by the Sdc1, and understanding the underlying molecular mechanism, besides the physiological phenomena of growth and development, is necessary in the pathological processes such as tumor cell invasion, angiogenesis, and metastasis." (PMID 30151336, 2018). "A limitation of our study is that later time points along the AOM-DSS induced colon tumorigenesis were not analyzed; such analyzes would potentially enable to test whether Sdc1 loss also affects tumor invasiveness, in addition to tumor growth, which is the focus of the present investigation." (PMID 28350804, 2017). "The loss of SDC-1 at the cell-surface could also occur through a switch to translation of alternative, non-membranous isoforms, or by aberrant processing in an advanced tumor." (PMID 24524203, 2014). "The co-option of SDC4 for mechanotransduction and SDC1 for immune evasion underscores their contextual specialization within the tumor microenvironment." (PMID 41561769, 2025). "A systematic pan-cancer analysis of SDC1 mRNA expression in normal and tumor tissues was conducted using the TCGA dataset. of 33 cancers had significantly different expression was observed." (PMID 41364407, 2025). "Most B lymphocytes were derived from the PPLELC tumor and defined into three subsets: plasma (SDC1), follicular B cells (FCER2) and germinal centre (GC) B cells (BCL6)." (PMID 40057671, 2025). "The distribution of patient and tumor characteristics was analyzed in relation to SDC1 staining in tumor and stromal cells." (PMID 41364407, 2025). "Several supermere‐specific proteins, such as THBS4, SDC1 and GPC1, are implicated in tumor progression, cell adhesion and intercellular signaling and have been detected in tumor‐derived EVs in previous studies." (PMID 41039818, 2025).
tumor (continued). "On the tumour cell surface, transmembrane SDC1 functions as a receptor capable of directly regulating downstream signalling pathways, including the PI3K-Akt and Rap1 pathways identified in this study." (PMID 41209699, 2025). "Functional experiments investigated the role of SDC1, a critical mediator of fibroblast-tumor crosstalk." (PMID 40616092, 2025). "Methylation analysis demonstrated that the expression of methylated SDC1 expression was much higher in tumor tissue than in normal tissue in KIRP." (PMID 41364407, 2025). "Concerning IL-2 immunocytokines combined with anti-angiogenic treatments, the critical role of the cell surface heparan sulfate proteoglycan syndecan-1 (SDC1, CD138) in neovascularization, vasculogenic mimicry (VM), and tumor progression is well established." (PMID 39852848, 2025). "This study elucidated the molecular mechanism by which SDC1 promotes tumor progression through multidimensional modulation of the TNBC microenvironment." (PMID 41209699, 2025). "For mechanistic insights, scRNA-seq was employed to map SDC1-dependent alterations in the tumor microenvironment (TME) immune architecture." (PMID 41209699, 2025). "Much due to its decade-long history as a gold-standard surface marker to detect MM cells in the bone-marrow and in peripheral blood, Syndecan-1/CD138 is an undiscussed prognostic factor in such tumour entity, when considered alone or in combination with CD38." (PMID 39980017, 2025). "Using the Sangerbox platform, we investigated the relationship between SDC1 expression and tumor stemness scores across six dimensions." (PMID 41364407, 2025). "This work pursued mechanistic evidence that SDC1 silencing with shRNA vectors disrupts tumor vascularization." (PMID 41209699, 2025). "Treatment with 200 ng/mL of SDC1 led to the strongest promotion of tumor cell proliferation, while a concentration of 500 ng/mL suppressed cell proliferation, likely due to cytotoxic effects." (PMID 40616092, 2025). "We further analyzed the correlation between SDC1 and cellular senescence in the tumor microenvironment of TNBC." (PMID 41209699, 2025). "While recognising the critical role of soluble SDC1 in tumour metastasis, this study focuses on the novel functions of transmembrane SDC1 in TNBC chemotherapy response and microenvironment regulation." (PMID 41209699, 2025). "Tumor cell membrane that expressed syndecan-1 (CD138) can bind to CD31 on endothelial cells for crossing the BBB." (PMID 41333818, 2025). "From mechanistic perspective, SDC1 expression levels were correlated with DNA methylation, immune cell infiltration and tumor cell stemness in multiple cancer types based on TCGA dataset." (PMID 41364407, 2025). "For example, sortilin and syndecan-1 have attracted attention for their high tumor sensitivity/specificity and roles in modulating glucose and lipid metabolism, cell proliferation, and tumor progression." (PMID 41303628, 2025). "SDC1 co-expression networks were studied using TCGA database to verify the potential function of SDC1 in tumor tissue." (PMID 41364407, 2025). "Molecular studies have demonstrated the role of E-cadherin and syndecan-1 as potential markers for tumor growth in canine squamous cell carcinoma, offering in-depth insights into its pathogenesis." (PMID 41394861, 2025). "IHC detection confirmed the presence of SDC1 in nearly all carcinoma areas, with prominent localization within the tumor cell cytoplasm." (PMID 41364407, 2025). "Syndecans, including SDC1, exhibit variable expression in several solid tumors and hematologic cancers, with high expression of SDC1 in the cytoplasm of tumor cells correlating with better patient survival." (PMID 40616092, 2025). "Tumor cells were identified using SDC1 as a marker, while immune cells were characterized using PTPRC." (PMID 40376263, 2025). "On the other hand, decreased epithelial expression of SDC1 showed tumor aggressiveness in head and neck cancer cells." (PMID 40542654, 2025).
tumor (continued). "Soluble (shed) syndecan-1 actively promoted inflammation, angiogenesis, tumor cell growth, and metastasis." (PMID 41357480, 2025). "Despite these constraints, our results provide initial insights into the expression of syndecan-1 and E-cadherin in canine cutaneous tumors, laying the groundwork for further investigations into their roles in tumor progression and prognosis." (PMID 39728992, 2024). "Conversely, syndecan-1 expression in the tumor stroma can enhance tumor angiogenesis by binding to growth factors like basic fibroblast growth factor." (PMID 39728992, 2024). "The results showed that the intensity of syndecan-1 decreased with increasing tumor aggressiveness, and its presence in the stroma was significantly associated with tumor grade." (PMID 39728992, 2024). "SDC1 (syndecans), a member of the type I transmembrane protein family, has higher expression in gliomas than normal brain tissue and is related with tumor aggressiveness and poor prognosis." (PMID 38396140, 2024). "SDC1 was employed to further improve the stroma and tumor targeting of LB-MSN-GEM/HNK, in which the uptake of GEM and HNK were significantly increased through SDC1/IGF1R receptor-mediated endocytosis." (PMID 38338418, 2024). "Particularly, SDC1 expression in human gliomas corresponds with advanced tumor progression and poor prognosis." (PMID 38816839, 2024). "High levels of SDC1 can lead to tumour cell proliferation, invasion and drug resistance, which are related to bad prognoses." (PMID 38822457, 2024). "The regression model findings identified syndecan-1 stromal positivity and E-cadherin intensity as significant predictors of tumor aggressiveness." (PMID 39728992, 2024). "Second, although the role of the HS chain of SDC-1 in infectious, inflammatory, and neoplastic diseases have been the most studied, studies have also reported the role of the core protein and the CS chain in these diseases." (PMID 39273320, 2024). "Syndecan-1 staining was primarily observed in the cytoplasm and membrane of tumor cells, with occasional nuclear localization." (PMID 39728992, 2024). "SDC1 was first grafted on the LB-MSN to further improve the stroma and tumor targeting of nanoparticles through SDC1/IGF1R receptor-mediated endocytosis." (PMID 38338418, 2024). "Identifying new biomarkers, such as syndecan-1 (CD138) and E-cadherin, is fundamental for tumor diagnosis and prognosis." (PMID 39728992, 2024). "The results showed that ITGA1, ITGB1, ITGB8 and SDC1 were highly expressed in tumor cells when compared with control group." (PMID 38526745, 2024). "The tumor growth inhibition index of SDC1-LB-MSN-GEM/HNK was 56.19%, which was 1.45-fold and 1.33-fold higher than that of the free GEM/HNK and LB-MSN-GEM/HNK treatment groups, respectively." (PMID 38338418, 2024). "The positive expression of SDC1 in tumor cells was significantly related to a poor prognosis and lower frequencies of TILs." (PMID 37069585, 2023). "Stromal SDC1’s role in primary tumor evolution to metastatic dissemination has also been suggested in humans." (PMID 36980680, 2023). "SDC1 knockdown significantly reduced tumor dissemination to the brain by modifying tumor cell secretion of cytokines and chemokines, which negatively impacts tumor cell migration across the blood–brain barrier." (PMID 36980680, 2023). "Targeting SDC1 to regulate tumor cells, CAFs, and TILs should be a promising research direction for TNBC treatment." (PMID 37069585, 2023). "YKL-40 functions as a pro-angiogenic factor to promote tumor angiogenesis via interacting with syndecan-1 or IL-13R2α." (PMID 37686533, 2023). "CD138, also known as Syndecan-1, is a type I transmembrane proteoglycan cell adhesion molecule overexpressed on transformed plasma cells that promotes angiogenesis, tumor growth and metastases, and adhesion to the TME, making it a viable target." (PMID 37111346, 2023).